PPARA (peroxisome proliferator activated receptor alpha)
Diseases named in the same sentence as PPARA in open-access papers (continued):
Sharing a sentence is not in itself a finding about the gene and the disease.
hepatocellular carcinoma (continued). "Peroxisome proliferator activated receptor α (PPARα) is a major transcriptional regulator of FAO and extended PPARα activation causes hepatocellular carcinoma by involving the perturbation of the cell cycle and the production of ROS." (PMID 36613455, 2022). "Studies in hepatocellular carcinoma have shown that long-chain noncoding RNA HULC can activate ACSL1 by upregulating the transcription factor PPARA to affect the proliferation of liver cancer cells." (PMID 33688464, 2021). "In human hepatoma cells, the major transcription regulator of lipid metabolism PPARα incorporates with SREBP in regulating MSMO1 expression." (PMID 34759952, 2021). "For example, lncRNA LINC00467 regulates the progression of hepatocellular carcinoma by regulating the expression of miR‐9‐5p/PPARA." (PMID 34264003, 2021). "In human-derived hepatoma cells, ER-β directly downregulates peroxisome proliferator-activated receptor-α (PPARα) gene expression and inhibits nuclear translocation, suppressing proliferation and inducing apoptosis." (PMID 34202146, 2021). "In that study, the AMPK activators, AICAR, and metformin decreased basal and WY-14,643-stimulated PPARα activity in hepatoma cells." (PMID 32708786, 2020). "Previous studies suggest that PPARα exerts anti-tumor effects in hepatoma cells by regulating NF-κB signaling." (PMID 32192216, 2020). "Low expression of PPARA is related to the proliferation, invasion and migration of hepatocellular carcinoma cells." (PMID 32650755, 2020). "All the PPAR subtypes (PPARα, PPARγ, and PPARδ) are constitutively expressed in FaO rat hepatoma cells." (PMID 32532017, 2020). "In this case, HULC stimulates the accumulation of intracellular triglycerides and cholesterol through the miR-9/PPARα/ACSL1 signaling pathway in hepatoma cells." (PMID 30134946, 2018). "The specific model systems used to study PPARα in human liver vary from hepatoma cell lines such as HepG2 to human primary hepatocytes, human precision cut liver slices, and mice expressing human PPARα." (PMID 29879903, 2018). "In Huh-7 hepatoma cells, PPARα in synergy with another nuclear receptor, that is, LRH-1 (liver receptor homolog-1), was proposed also to drive miR-200c transcription through a direct binding to its promoter." (PMID 28167956, 2017). "Using H4IIEC3, a PPARα-responsive hepatoma cell line, we demonstrated that α-ESA reduced intracellular triglyceride accumulation by increasing mRNA concentrations and enzyme activity of PPARα target genes after 24 or 48 h of treatment." (PMID 27973445, 2016). "We previously demonstrated that α-ESA, as compared to α-linolenic acid (fatty acid control), reduced triglyceride concentrations in H4IIEC3, a PPARα-responsive hepatoma cell line." (PMID 27973445, 2016). "This is similar to humans but significantly different from the rodent species in which activation of PPARα by clofibrate initiates hepatocyte proliferation and induces the well-known hepatocellular carcinoma." (PMID 25883783, 2015). "Experiments in vitro, using hepatoma cells stimulated with peroxisome proliferator activated receptor alpha (PPARα) agonist WY14,643, revealed a significantly reduced Cbs mRNA expression." (PMID 23472083, 2013). "On the other hand, hepatocellular carcinoma or hepatomegaly has been known to occur when PPARα agonists were administered for a long time to mice or rats." (PMID 23316217, 2012). "The present investigation indicated increased expression of PPARα mRNA and mRNAs for PPARα target genes in human hepatocellular carcinoma." (PMID 22168458, 2011).
hepatocellular carcinoma (continued). "The aim of the present study was to identify changes in gene expression profiles induced by PPARγ and PPARα/γ agonists in human hepatocytes from several donors and in differentiated human hepatoma HepaRG cells using a whole genome transcriptomic approach." (PMID 21533120, 2011). "Persistent activation of PPARα has also been suggested for the pathogenesis of hepatic steatosis and hepatocellular carcinoma in HCV core expressing transgenic mice." (PMID 21994721, 2010). "All these responses, including the development of hepatocellular carcinomas, are receptor mediated and achieved through selective activation of PPARα." (PMID 20885938, 2010). "As lipid metabolism of hepatoma cell lines is dramatically lower than that of primary hepatocytes, we studied the metabolic aspects of PPARα and LXRα regulation in primary rat hepatocytes." (PMID 20811644, 2010). "In rat hepatoma cells, acetaldehyde inhibited PPARβ/δ DNA binding activity but at a much higher concentration than that required for PPARα inhibition." (PMID 19756185, 2009). "In cultured hepatoma cells ethanol affects PPARα transcriptional activity by inhibiting the ability of the receptor to bind its PPRE consensus sequences." (PMID 19756185, 2009). "In general, research on the role of PPARα in human liver is hampered by the low expressionlevels of PPARα in human hepatoma cell lines." (PMID 17389767, 2007). "Notably, targeting the CES1/PPARα/stearoyl-CoA desaturase 1 pathway has been reported to enhance the efficacy of cisplatin in hepatocellular carcinoma models, with coadministration reducing tumor growth in xenografted mice." (PMID 40650205, 2025). "RAN was shown to interact with both CRM1 and PPARα in hepatoma cells." (PMID 40069732, 2025). "In contrast, the induction of apoptosis in hepatocellular carcinoma cells via the overexpression of PPARα was dependent on NF-κB signaling, as PPARα was found to directly interact with IκBα (nuclear factor kappa-light-polypeptide-gene-enhancer in B-cells inhibitor alpha)." (PMID 35954274, 2022). "Similarly, in hepatic carcinoma cells, apoptosis was induced by the flavonoid quercetin, which downregulated PPARα expression." (PMID 35954274, 2022). "Moreover, it has been shown that fenofibrate suppresses growth via a decrease in phosphorylation of Akt, and this effect is PPARα independent in hepatocellular carcinoma cells as well as in angiosarcoma cells." (PMID 34572440, 2021). "LINC00467, a greatly concerned LncRNA in cancer-related research recently, has been demonstrated to promote lung adenocarcinoma proliferation by sponging miR-20b-5p to activate CCND1 expression, regulate hepatocellular carcinoma progression by modulating miR-9-5p/PPARA expression." (PMID 33996559, 2021). "NAFLD/NASH may progress to liver cirrhosis and hepatocellular carcinoma, and PPARα may influence the severity of NAFLD/NASH." (PMID 32192216, 2020). "Acyl-CoA synthase long-chain (ACSL) family members catalyze the initial step in cellular long-chain FA metabolism in mammals; ACSL1, one of the major isoforms of the ACSL family, can increase the uptake of FAs in hepatoma cells and can be regulated by the transcriptional factor PPARα." (PMID 30134946, 2018). "Since the PPARα agonist GW7647 increased PDZK1 expression in Huh-7 hepatoma cells, as well as in Caco-2BBE cells, it is possible that the positive effect of RA on PDZK1 expression exerts its effect via binding of RXRα to the PPRE element as well as the RARE element." (PMID 28223944, 2017). "In this model, by knocking down PPARα, the development of hepatocellular carcinoma was suppressed." (PMID 23316217, 2012). "In rodents, however, fibrate drugs cause hepatomegaly and eventually hepatic carcinoma, which is not seen in humans, and is reflected in a much lower level of expression of PPARα and thus a different balance between PPARα and PPARδ in the human liver." (PMID 22550474, 2012).
hepatocellular carcinoma (continued). "Chronic activation of PPARα in rodents leads to the development of hepatocellular carcinomas." (PMID 20885938, 2010). "Long-term pharmacological activation of PPARα by Wy-14,643 in mice leads to marked peroxisome proliferation, hepatocyte hyperplasia, and a high incidence of hepatocellular carcinoma (HCC) in over 70% of wild-type mice." (PMID 40565288, 2025). "Besides that, PPARα was proved anti-tumor effects in hepatoma cells by regulating NF-κB signaling." (PMID 35414769, 2022). "Related reports revealed that most core DMEs were positively correlated with AHR, PXR and PPARα, and their protein expression was downregulated in nearly 50% of the patients with hepatocellular carcinoma (HCC)." (PMID 33240601, 2020). "To further examine the underlying mechanisms causing an upregulation of BHMT and a downregulation of CBS, we explored whether PPARα-activation by the agonist WY14,643 in rat hepatoma cells (Fao) can cause similar changes in gene expression in vitro as observed in the livers of obese mice." (PMID 23472083, 2013). "To date, deletion of Med1 in liver has been shown to abrogate the ability of PPARα to activate transcription of target genes as well as block other pleiotropic effects of receptor activation including liver regeneration and the development of hepatocellular carcinoma." (PMID 20885938, 2010). "Interestingly, in rat FAO hepatoma cells, it was found that PPARα activation reduced expression of lipogenic genes, including Fasn, Gpam, and SREBP1c, while Insig1 expression was increased by PPARα." (PMID 20936127, 2010). "Additionally, human hepatoma HepG2 cells were shown to respond poorly to PPARα activation." (PMID 19710929, 2009). "Furthermore, the hsa-miR-21-5p/PPARα pathway was similarly dysregulated in patients with hepatocellular carcinoma (HCC)." (PMID 41095675, 2025). "It has the potential to be effective in treating certain types of cancer, such as hepatocellular carcinoma (HCC) and renal cell carcinoma (RCC), where COX-2 and PPARα are overexpressed." (PMID 39660001, 2024). "In hepatocellular carcinoma (HCC) and renal cell carcinoma (RCC), both COX-2 and PPARα are overexpressed." (PMID 39660001, 2024). "HULC (highly upregulated in liver cancer) is an lncRNA specifically overexpressed in HCC; HULC upregulates PPARα to activate acyl-CoA synthetase subunit ACSL1, thereby aberrantly modulating lipid metabolism in hepatoma cells and in the development of HCC." (PMID 39199690, 2024). "In hepatocellular carcinoma (HCC), lncRNA HULC forms a positive feedback loop to promote adipogenesis and enhance tumor proliferation through the HULC/miR-9/PPARA/ACSL1/cholesterol/RXRA/HULC pathway." (PMID 36452489, 2022). "As SCD1 was reported to act as a functional downstream factor of PPARα and is involved in the maintenance of CSCs in hepatocellular carcinoma (HCC), the PPARα–SCD1 axis may be one of the important pathways in the maintenance of CSCs." (PMID 33466690, 2021). "For example, the Highly Up-Regulated In Liver Cancer long non-coding RNA (LncRNA-HULC) is able to activate acyl-CoA synthetase subunit ACSL1, involving also in this process miR-9 and PPARA, contributing to the malignant development of hepatocellular carcinoma (HCC)." (PMID 33050166, 2020). "Constitutive activation of PPARα activated FAO, and the subsequent production of ATP and ROS contributed to the pathogenesis of hepatocellular carcinoma (HCC)." (PMID 30771209, 2019). "In hepatoma cells, HULC suppresses miR-9 targeting PPARα silencing by eliciting the methylation of CpG islands in the miR-9 promoter, and PPARα activates ACSL1 transcription." (PMID 30134946, 2018). "MIR-27a was described to be involved in lipid metabolism, by regulating RXRα, PPARα/γ, FASN, SREBP1, SREBP2, and was able to inhibit HCV replication in human hepatoma cells." (PMID 26728044, 2016). "We investigated the functional significance of PPARα in hepatocellular carcinoma (HCC)." (PMID 25327562, 2014).
hepatocellular carcinoma (continued). "In summary, results of the current study confirm the positive effects that PPARα agonists exert on UGT1A1 expression and support a similar response of the MRP2 gene, at least in human hepatocytes and hepatoma HepG2 cells." (PMID 25147562, 2014). "Furthermore, TNFα and IL1β treatment of Hep3B human hepatoma cells and mice resulted in decreased expression of RXRα, PPARα, PPARγ, LXRα, as well as their co-activators PGC1α and PGC-1β, which may contribute to the cytokine induced modulations in hepatic energy homeostasis." (PMID 24112857, 2013). "The mRNA abundance of PPARα-target genes that control fatty acid oxidation, such as CYP4A11, ACOX, and UCP1 significantly increases in human hepatoma cells." (PMID 20811644, 2010). "We show that naringenin induces the activation of PPARα and PPARγ ligand-binding domain (LBD) in GAL4-fusion protein reporters and induces PPRE activity in Huh7.5 human hepatoma cells." (PMID 20811644, 2010). "In addition, Slc25a47 expression was significantly induced by PPARα activation in mouse hepatocytes, rat FAO hepatoma cells, and mouse liver." (PMID 39746607, 2025). "In hepatocellular carcinoma (HCC), suppression of CES1 leads to a significant reduction in lipid signaling molecules of PPARα/γ, with a notable downregulation of the PPARα/γ target gene SCD, which is associated with tumor metastasis, recurrence, and chemoresistance." (PMID 39472448, 2024). "A negative correlation between the expressions of CD147 and PPARα was reported in hepatocellular carcinoma." (PMID 35898887, 2022). "As the inhibition of PPARα did not modify these results, it is likely that fenofibrate had a PPARα-independent effect as was also shown in hepatocellular carcinoma cells." (PMID 35954274, 2022). "Consequently, a knockout of PPARα and the inhibition of fatty-acid oxidation using the CPT-1 inhibitor etomoxir reduced hepatocellular carcinoma progression." (PMID 35954274, 2022). "Moreover, the activation of ATGL disrupts lipolysis in hepatocellular carcinoma cells, which is accompanied by the activation of DAG (diacylglycerol) + FFA (free fatty acids)/PPARα (peroxisome proliferator-activated receptor alpha) signaling." (PMID 36362406, 2022). "Accumulating evidence shows that long-term activation of PPARα induces hepatocellular carcinoma in rodent, but not human, liver, suggesting that disorders in lipid metabolisms can be implicated in carcinogenesis." (PMID 34360635, 2021). "Moreover, pterostilbene, a bioactive component of blueberries and grapes and an agonist of PPARα, activates AMPK, similarly to AICAR and metformin, and modulates several AMPK-dependent metabolic functions in the rat hepatoma cell line H4IIE." (PMID 32708786, 2020). "It is interesting to note that HepG2 cells, derived from a human hepatocellular carcinoma, showed constitutive expression of both PPARα and D6D, which is not unexpected in cells that retain many liver-specific characteristics, including fat metabolism." (PMID 30872768, 2019). "HULC upregulates the transcriptional factor peroxisome proliferator-activated receptor alpha (PPARA) which increases acyl-CoA synthetase long-chain family member 1 (ACSL1), leading to triglycerides and cholesterol production and proliferation of hepatoma cells." (PMID 28840253, 2018). "In our experience, PPARα activation is unlikely to play any significant role in CF-induced apoptosis of Jurkat (this report) or hepatoma cells, particularly in view of its very rapid time-course." (PMID 23028936, 2012). "We assessed the expression of PPARα mRNA in human hepatocellular carcinoma tissue and non-cancerous tissue, as well as the expression of target genes of PPARα, carnitine palmitoyltransferase 1A and cyclin D1 mRNAs." (PMID 22168458, 2011). "In contrast, activation of PPARα in humans does not seem to induce hepatocellular carcinomas, suggesting a species specific response to PPARα activation." (PMID 20936127, 2010).
hepatocellular carcinoma (continued). "The other study showed that incidence of DEHP-induced hepatocellular carcinomas in PPARα-null mice was significantly higher than in wild type mice, suggesting negative relationship between PPARα expression and cell proliferation." (PMID 19672312, 2009). "In hepatoma cells, genetic knockout of CD147 reduced fatty acid synthesis by disrupting the Akt/mTOR signaling pathway and upregulating peroxisome proliferator-activated receptor α (PPARα), thereby increasing proliferation and metastasis formation in cell lines and mouse models." (PMID 40881692, 2025). "In addition, long-term activation of PPARα leads to excessive cell proliferation and development of liver tumors, particularly hepatocellular carcinoma, which is primarily observed in rodents and not readily translated to humans." (PMID 40815899, 2025). "A latest study showed that the activation of mitochondrial fission downregulated PGC-1α/PPARα signaling in hepatocellular carcinoma (HCC) cells and inhibited SIRT1 driving metabolic reprogramming in HCC." (PMID 36647167, 2023). "Besides the upregulation of PPARα in hepatoma cell lines with ACOX2 overexpression, no mechanistic link between the two proteins has been explored." (PMID 35954274, 2022). "Hepatocellular carcinoma upregulated long non-coding RNA (HULC) is highly upregulated in hepatocellular carcinoma and sequesters several miRNAs, including miR-9, leading to de-repression of its target, PPARA, which induces a positive feedback loop involving ACSL1." (PMID 27487126, 2017). "The down-regulation of insulin signaling and PPARα transcription in this analysis reflects the increased expression of gluconeogenesis and lipid synthesis and trafficking genes in the hepatoma cells following Tcf7l2 silencing, as both a negative regulators of these pathways." (PMID 25414334, 2014). "Regarding to the mechanistic role of PPARα in our study, we could demonstrate in hepatoma cells using the PPARα agonist WY14,643 that Cbs is a target gene of the PPARα signaling pathway leading to a downregulation of the transsulfuration pathway comparably as shown by low CBS levels in HF mice." (PMID 23472083, 2013). "Indeed, expression of precursors or antisense nucleotides for miR-21, or miR-27b, in Huh-7 hepatoma cells could significantly modulate the expression of PPARα protein, but not its mRNA, suggesting a blockade of PPAR mRNA translation by miR-21/-27b." (PMID 23024649, 2012). "In the context of liver pathology, PPARα was demonstrated to be a direct target of miR-155 or miR-21 in mouse biliary, hepatic and inflammatory cells in a mouse model of alcohol-induced steatohepatitis, NASH and in the development of hepatocellular carcinoma (HCC)." (PMID 36139455, 2022).